ZNF696 (zinc finger protein 696)
Description:
May be involved in transcriptional regulation.
Synonyms: FLJ14129
Tractability: PROTAC: ubiquitination databases record sites on it.
Gene: Protein-coding gene on chromosome 8 (143,289,676 to 143,299,952, forward strand). Ensembl gene ENSG00000185730.
Subcellular location: Nucleus
Subcellular location (Human Protein Atlas): Nucleoplasm; Nucleoli
Pathways (Reactome):
Gene expression (Transcription): Generic Transcription Pathway
Gene Ontology:
Molecular function: protein binding; DNA-binding transcription factor activity, RNA polymerase II-specific; RNA polymerase II transcription regulatory region sequence-specific DNA binding
Biological process: regulation of transcription by RNA polymerase II
Cellular component: nucleus
Genetic constraint (gnomAD): Loss-of-function variants: 21 observed, 14.91 expected, observed/expected ratio (o/e) 1.41, 90% interval 0.99 to 1.88. The synonymous counts are far from expectation, so gnomAD's model fits this gene poorly and the ratio says little. Missense variants: 578 observed, 396.65 expected, observed/expected ratio (o/e) 1.46, 90% interval 1.36 to 1.56. Synonymous variants: 253 observed, 163.18 expected, observed/expected ratio (o/e) 1.55, 90% interval 1.4 to 1.72.
Homologues: Orthologues: chimpanzee ZNF696 (98% identical), macaque ZNF696 (91% identical), pig ZNF696 (65% identical). Paralogues in human: ZNF16 (39% identical), ZNF229 (39% identical), ZNF250 (39% identical), ZNF189 (38% identical), ZNF568 (38% identical), ZFP3 (38% identical), ZNF30 (38% identical), ZNF623 (38% identical), ZNF33B (38% identical), ZNF41 (38% identical), ZNF658 (38% identical), ZNF429 (37% identical), and 164 more.
Diseases named in the same sentence as ZNF696 in open-access papers:
ZNF696 is named in the same sentence as 7 diseases in open-access papers, as found by Europe PMC text mining. Sharing a sentence is not in itself a finding about the gene and the disease. The quoted sentences say what the papers report.
asthma (1 paper, 2022). "Therefore, these genes can increase the odds and show an up-regulated effect on the outcome of asthma, while 40 genes including CNBP, POLL, ZNF696, HUS1 among others impose a down-regulated effect on the disease response." (PMID 35606385, 2022).
gestational diabetes mellitus (1 paper, 2021). "In conclusion, gestational diabetes mellitus is associated with DNA methylation changes at the alternative transcription start site of ZNF696 in cord blood cells." (PMID 34267729, 2021).
nasopharyngeal carcinoma (1 paper, 2021). A carcinoma arising from the nasopharyngeal epithelium. "Although the function of ZNF696 remains unknown, a previous study reported that this gene is involved in acquired paclitaxel resistance in nasopharyngeal carcinoma cells." (PMID 34267729, 2021).
serous ovarian carcinoma (1 paper, 2025). "ZNF696, a zinc finger protein located on chromosome 8q24.3, has recently been identified as a significant amplified driver gene in high-grade serous ovarian carcinoma (HGSOC)." (PMID 41303609, 2025).
cancer (1 paper, 2022). A tumor composed of atypical neoplastic, often pleomorphic cells that invade other tissues. "Significantly altered functions, pathways, and gene networks revealed alterations in several key genes and cancer-related pathways that may have importance for NSCLC transformation, including FAM83A, ZNF696, UBE2C, RECK, TIMM50, GEMIN7, and XPO5." (PMID 35309509, 2022). "Moreover, gene interaction networks revealed several key genes and cancer-related pathways that may role for early NSCLC transformation and disease progression, including FAM83A, ZNF696, UBE2C, RECK, TIMM50, GEMIN7, and XPO5." (PMID 35309509, 2022).
ZNF696 also shares sentences with these, for which no sentence is quoted: Hypoglycemia (1 paper); lung carcinoma (1).